Y_RNA (Y RNA )
Gene: Miscellaneous RNA gene on chromosome 10 (88,585,638 to 88,585,733, reverse strand). Ensembl gene ENSG00000201548.
Homologues: Orthologues: chimpanzee Y_RNA (98% identical), macaque Y_RNA (94% identical). Paralogues in human: Y_RNA (90% identical), RNY4P7 (89% identical), RNY4 (88% identical), RNY4P14 (88% identical), RNY4P3 (88% identical), Y_RNA (88% identical), RNY4P10 (85% identical), RNY4P25 (85% identical), RNY4P6 (85% identical), Y_RNA (85% identical), RNY4P27 (84% identical), Y_RNA (84% identical), and 90 more.